HEXIM1 (HEXIM P-TEFb complex subunit 1)
Description:
Transcriptional regulator which functions as a general RNA polymerase II transcription inhibitor. Core component of the 7SK RNP complex: in cooperation with 7SK snRNA sequesters P-TEFb in a large inactive 7SK snRNP complex preventing RNA polymerase II phosphorylation and subsequent transcriptional elongation. May also regulate NF-kappa-B, ESR1, NR3C1 and CIITA-dependent transcriptional activity. Plays a role in the regulation of DNA virus-mediated innate immune response by assembling into the HDP-RNP complex, a complex that serves as a platform for IRF3 phosphorylation and subsequent innate immune response activation through the cGAS-STING pathway.
Synonyms: EDG1; HIS1; MAQ1; CLP-1
Tractability: Small molecule: it has a binding pocket of medium quality. PROTAC: ubiquitination databases record sites on it; its protein half-life has been measured.
Gene: Protein-coding gene on chromosome 17 (45,148,475 to 45,152,099, forward strand). Ensembl gene ENSG00000186834.
Subcellular location: Nucleus; Cytoplasm
Subcellular location (Human Protein Atlas): Nucleoplasm; Vesicles
Gene Ontology:
Molecular function: 7SK snRNA binding; cyclin-dependent protein serine/threonine kinase inhibitor activity; identical protein binding; P-TEFb complex binding; protein binding; protein kinase inhibitor activity; snRNA binding; transcription regulator inhibitor activity
Biological process: activation of innate immune response; negative regulation of transcription by RNA polymerase II; negative regulation of transcription elongation by RNA polymerase II; negative regulation of viral transcription
Cellular component: 7SK snRNP; cytoplasm; nucleoplasm; nucleus
Genetic constraint (gnomAD): Loss-of-function variants: 1 observed, 32 expected, observed/expected ratio (o/e) 0.0313, 90% interval 0.01 to 0.15. The upper end of that interval is the gene's LOEUF score, 0.15, which puts it in group 1 of 6, group 1 being the genes least tolerant of losing a copy. Missense variants: 391 observed, 510.93 expected, observed/expected ratio (o/e) 0.77, 90% interval 0.7 to 0.83. Synonymous variants: 245 observed, 223.63 expected, observed/expected ratio (o/e) 1.1, 90% interval 0.99 to 1.22.
Homologues: Orthologues: chimpanzee HEXIM1 (100% identical), macaque HEXIM1 (98% identical), pig HEXIM1 (87% identical), mouse Hexim1 (85% identical), rat Hexim1 (85% identical), guinea pig HEXIM1 (52% identical), zebrafish hexim1 (41% identical), tropical clawed frog hexim1 (40% identical), Drosophila melanogaster Hexim (20% identical). Paralogues in human: HEXIM2 (35% identical).
Diseases named in the same sentence as HEXIM1 in open-access papers:
HEXIM1 is named in the same sentence as 39 diseases in open-access papers, as found by Europe PMC text mining. Sharing a sentence is not in itself a finding about the gene and the disease. The quoted sentences say what the papers report.
breast carcinoma (12 papers, 2013 to 2023). "HEXIM1 was found to associate with estrogen receptor α (ERα), which is widely targeted in breast cancer therapy." (PMID 26734838, 2016). "Immunohistochemical studies using the samples of breast cancer patients showed that lower expression of HEXIM1 was associated with tumor recurrence in tamoxifen-receiving patients, suggesting that HEXIM1 is a critical determinant of tamoxifen resistance." (PMID 24592384, 2014). "When associated with HEXIM1, the transcriptional activity of ERα is inhibited, suggesting a role of HEXIM1 in breast cancer." (PMID 24202322, 2013). "We determined that 5-AzadC-induced DNA damage resulted in upregulation of the tumor suppressor HEXIM1, and established a role for the DNA damage response pathway in the transcriptional regulation of HEXIM1 in prostate and breast cancer cells." (PMID 33273553, 2020). "KDM5B inhibition promoted the re-expression of tumor suppressor protein HEXIM1, and upregulated HEXIM1 aided in the inhibition of breast cancer cell proliferation using KDM5B inhibitors." (PMID 32751840, 2020). "We also observed 5-AzadC-induced HEXIM1 expression in breast cancer cells representative of the luminal subtype, MCF7 and T47D." (PMID 33273553, 2020). "Downregulation of NF-ĸB attenuated 5-AzadC-induced HEXIM1 expression in prostate and breast cancer cells." (PMID 33273553, 2020). "HEXIM1 expression is also decreased in metastatic breast cancer, and re-expression of HEXIM1 resulted in the inhibition of mammary tumor growth and metastasis." (PMID 33273553, 2020). "Upregulation of HEXIM1 expression levels plays an essential role in the inhibition of proliferation of breast cancer cells via KDM5B inhibitors." (PMID 31805991, 2019). "While HEXIM1 is expressed at somewhat higher levels less aggressive slower growing subtypes such as normal-like and luminal breast cancer, HEXIM1 levels are notably decreased in the faster growing subtypes such as HER2 enriched and basal/TNBC breast cancer." (PMID 31805991, 2019). "Upregulation of HEXIM1 expression levels plays a critical role in the inhibition of proliferation of breast cancer cells using KDM5B inhibitors." (PMID 31805991, 2019). "KDM5B is overexpressed in breast cancer and thus likely inversely correlated with HEXIM1 expression." (PMID 31805991, 2019). "Our results show that HEXIM1 BR peptide exhibits specific cell killing when directed by a breast cancer targeting peptide, suggesting the use of the BR peptide in anti-tumor strategies." (PMID 26734838, 2016). "As reported recently, HEXIM1 expression is required for enhancing the response to tamoxifen treatment in breast cancer patients." (PMID 27176767, 2016). "In this study, we evaluate the potential use of the HEXIM1 BR peptide as the therapeutic peptide against breast cancer." (PMID 26734838, 2016). "They identified HEXIM1 as a novel binding protein of estrogen receptor α (ERα) in a yeast two-hybrid screen using a cDNA library of MCF7 breast cancer cells." (PMID 24592384, 2014). "As downregulation of HEXIM1 in human breast cancer has been reported previously, we focused on LARP7 in this study." (PMID 25053741, 2014). "A lower expression level of HEXIM1 was detected in metastatic breast cancers when compared with matched primary breast tumors." (PMID 24592384, 2014). "Of the known components in the three major P-TEFb-containing complexes, the 7SK snRNP, the Brd4-bound complex, and the SEC, only LARP7 and HEXIM1, two signature components of the 7SK snRNP, showed consistent alteration in human breast cancer tissues." (PMID 25053741, 2014). "HEXIM1 was also identified as a binding protein of estrogen receptor α (ERα) from a yeast two-hybrid screen using a MCF7 breast cancer cell cDNA library." (PMID 24202322, 2013).
breast carcinoma (continued). "Our data also suggest that upregulation of HEXIM1 expression levels plays a critical role in the inhibition of proliferation, differentiation, and regulation of expression of major growth regulatory factors in breast cancer cells by KDM5B inhibitors." (PMID 31805991, 2019). "Moreover, the ability of HEXIM1 to inhibit major tumor promoting pathways likely contributes to the effective targeting of multiple breast cancer subtypes with HEXIM1 inducers, alone or in combination with other therapeutics." (PMID 31805991, 2019). "In determining that HMBA and 4a1 induce HEXIM1 expression by counteracting the inhibitory effects of KDM5B upon HEXIM1 expression, we may have perhaps determined how HEXIM1 expression is lost in breast cancer." (PMID 31805991, 2019). "In addition, increased HEXIM1 expression correlates with a better prognosis and decreases probability of breast cancer recurrence." (PMID 27176767, 2016). "Thus, HEXIM1 induction is also a potential therapeutic approach for breast cancer." (PMID 33273553, 2020). "Therefore, a potential role of HEXIM1 in regulating ERα in breast cancers was suggested." (PMID 24592384, 2014). "To explore the potential use of the cytotoxic HEXIM1 BR peptide in cancer therapy, we fused a breast cancer targeting peptide LTV, to HEXIM1 BR and BR-RRR12 to generate the fusion peptides namely, LTV-BR and LTV-BR-RRR12." (PMID 26734838, 2016). "While we have reported on the expression of HEXIM1 in different grades of breast and prostate cancer, we have not reported on expression in different breast cancer subtypes." (PMID 31805991, 2019). "Breast cancer cells exhibited lower HEXIM1 expression when compared to normal breast epithelial tissue, and overexpression of HEXIM1 inhibited growth of both normal and breast cancer cells." (PMID 24592384, 2014). "Interestingly, HEXIM1 expression did not correlate with the malignant features of the breast cancer cell lines; it was moderately reduced in three invasive cancer lines and ZR75B non-invasive cancer line, but remained high in the metastatic MDA-MB-231 cells." (PMID 25053741, 2014).
melanoma (7 papers, 2018 to 2023). A malignant, usually aggressive tumor composed of atypical, neoplastic melanocytes. "In a previous study, HEXIM1 has been linked with nucleotide starvation, which was shown to sequester P-TEFb activity in melanoma." (PMID 31253180, 2019). "Consistent with our result, SP1 and HEXIM1 have been documented to play an important regulatory role in inhibiting melanoma-specific gene transcription." (PMID 37904237, 2023). "The melanoma tumor suppressor gene HEXIM1 is upregulated by obligatory binding of SP1 under nucleotide stress conditions." (PMID 37904237, 2023). "Tan and colleagues utilized Oncomine expression data to evaluate the role of candidate transcription elongation regulators in melanoma and found that HEXIM1 P-TEFb complex subunit 1 (HEXIM1) expression was significantly reduced in melanomas compared to nevi." (PMID 32455885, 2020). "Consistent with the possibility that HEXIM1 acts as a tumor suppressor, elevated expression of this gene using the MiniCoopR system delayed and Crispr/Cas9-mediated knockout accelerated melanoma onset." (PMID 32455885, 2020). "The anti-cancer actions of HEXIM1 in breast and prostate cancer, melanomas, and AML have been reported by our group and others." (PMID 31805991, 2019). "The tumor suppressor actions of hexamethylene bis-acetamide (HMBA)-inducible protein 1 (HEXIM1) in the breast, prostate, melanomas, and AML have been reported by our group and others." (PMID 31805991, 2019). "In addition, we analyzed the enrichment of transcription regulators with the 66 significant enhancers and found that several critical melanoma-associated TFs (e.g., SP1, SNAI2, HEXIM1, ASCL1) preferentially bind at these enhancer loci." (PMID 37904237, 2023). "The anti-cancer actions of HEXIM1 in melanomas and AML have been reported by other groups." (PMID 33273553, 2020). "In the zebrafish melanoma model study, it was found that knockout LARP7 could rescue melanocyte gene expression and observe melanocytes in knockout HEXIM1." (PMID 34107850, 2021).
cardiac hypertrophy (6 papers, 2009 to 2021). "The CLP-1/HEXIM1 null mutation is embryonic lethal in mice, and results in early cardiac hypertrophy." (PMID 27176767, 2016). "An insertional mutation in the Hexim1 gene resulting in disrupted C-terminal region in mice causes thin ventricular wall, and inducible postnatal expression of Hexim1 in the cardiomyocytes gives rise to physiological cardiac hypertrophy." (PMID 33199370, 2021). "For instance, the genetic deletion of the HEXIM1 murine homolog, CLP-1 (cardiac lineage protein 1), results in embryonic lethality and mimics the characteristics of cardiac hypertrophy." (PMID 34146121, 2021). "Genetic ablation of Clp-1, the mouse homologue of human Hexim1, resulted in embryonic death at E16.5 due to cardiac hypertrophy." (PMID 19723344, 2009). "Briefly, ectopic activation of P-TEFb either by ablation of cardiac lineage protein 1 (Clp-1), the mouse homologue of Hexim1, or overexpression of CycT1 in adult heart led to fetal lethality or heart growth due to cardiac hypertrophy, respectively." (PMID 19723344, 2009). "HEXIM1 is involved in many kinds of cancer, viral transcription of HIV-1, cardiac hypertrophy, and inflammation." (PMID 27176767, 2016). "Since HEXIM1 was supposed to be a negative modulator of P-TEFb and cardiac hypertrophy (See Introduction), we stimulated NRCM with ET-1, a potent inducer of cardiomyocyte hypertrophy, and effects of HEXIM1 and mtHEXIM1 were examined." (PMID 23300697, 2012). "Another type of transgenic mouse expressing mutant HEXIM1 lacking its C-terminal 49 amino acids created in the Montano laboratory (there, HEXIM1 is called “EDG1”) exhibits myocardial hypertrophy and heart failures." (PMID 32075058, 2020).
acute myelogenous leukemias (4 papers, 2013 to 2017). "Min Huang's research demonstrated the activation of autophagy as the cause of degradation of HEXIM1 in a subset of acute myelogenous leukemias, and verified its role in the regulation of HEXIM1 protein stability." (PMID 28484091, 2017). "Our data strongly support the activation of autophagy as the cause of degradation of NPM1, NPMc+, and HEXIM1 in a subset of acute myelogenous leukemias." (PMID 27732946, 2016). "Significant lower protein levels of HEXIM1 and NPM were observed in the acute myeloid leukemia cell line with NPMc+ mutant." (PMID 23977357, 2013).
breast tumor (3 papers, 2019 to 2023). "HEXIM1 has been identified as a tumor suppressor, and reducing its level of expression has appeared to be associated with resistance to tamoxifen in breast tumors, anti-androgens in prostate cancer, and increased progression and decreased therapeutic sensitivity in triple-negative breast cancer." (PMID 38203378, 2023). "We have also been studying the HEXIM1 as a breast tumor suppressor whose expression is decreased in tamoxifen resistant, triple negative, and metastatic breast cancer." (PMID 33273553, 2020). "Known inhibitors of KDM5B were also able to induce HEXIM1 expression, inhibit cell proliferation, induce differentiation, potentiate sensitivity to cancer chemotherapy, and inhibit breast tumor metastasis." (PMID 31805991, 2019). "HEXIM1 expression was previously inversely correlated with proliferative activity, as assessed via the expression of the prognostic marker Ki67, in all breast tumor grades." (PMID 31805991, 2019). "HEXIM1 expression was inversely related to proliferative activity in breast tumor tissue." (PMID 31805991, 2019).
insomnia (3 papers, 2021 to 2023). A sleep disorder characterized by difficulty in falling asleep and/or remaining asleep. "HEXIM1 is a transcription regulator suggested for its role in cancer and linked to insomnia, but its association with MDD still lacks." (PMID 34680902, 2021). "The study found that three shared genes i.e ITPR3, HEXIM1, and IQCH were involved between insomnia and asthma, while ITPR3 and HEXIM1 seem to be associated with an inflammatory response." (PMID 37163444, 2023). "We identified 62 variants linked to shared genetics of MDD and insomnia symptoms, with signals near MEIS1, RP11-6N13.1, OLFM4, HEXIM1, and TCF4 being the strongest." (PMID 34680902, 2021). "Among the shared genes, three genes, ITPR3, HEXIM1, and IQCH, were found to be reported in both GWASs of asthma and insomnia, and two genes, ITPR3 and HEXIM1 appear to be involved in the inflammation process." (PMID 34750467, 2021).
prostate carcinoma (3 papers, 2019 to 2023). A carcinoma that arises from epithelial cells of the prostate gland. "A similar mechanism as observed in prostate cancer cells involving induction of DNA damage is supported by the attenuation of the induction of HEXIM1 expression in TNBC cells in the presence of caffeine or NF-ĸB shRNA." (PMID 33273553, 2020). "As a consequence, 5-AzadC induced HEXIM1 expression in prostate cancer cell lines and triple negative breast cancers." (PMID 33273553, 2020). "We have been studying the role of Hexamethylene bisacetamide (HMBA) Induced Protein 1 (HEXIM1) as a tumor suppressor whose expression is decreased in breast and prostate cancer." (PMID 33273553, 2020). "HEXIM1 expression is decreased in hormone resistant breast and prostate cancer." (PMID 33273553, 2020). "Paradoxically, HEXIM1 upregulated KDM5B expression in prostate cancer." (PMID 31805991, 2019). "Of note, search of COSMIC and TCGA databases indicates that KDM5B and HEXIM1 mutations are not common occurrences in breast and prostate cancer." (PMID 31805991, 2019).
glioma (2 papers, 2017). A benign or malignant brain and spinal cord tumor that arises from glial cells (astrocytes, oligodendrocytes, ependymal cells). "The WST-1 assay verified that the effect of ubenimex-improved JQ1 sensitivity was attenuated (P<0.05) upon knockdown of HEXIM1 in glioma cells." (PMID 28484091, 2017). "In this study, we have discovered that ubenimex suppresses the Akt pathway and autophagy in glioma cell lines, resulting in reduced proteolysis of HEXIM1, increasing HEXIM1 expression and activity." (PMID 28484091, 2017). "Our research show definitive evidence to suggest that autophagy is central to HEXIM1 degradation in a subset of glioma cells." (PMID 28484091, 2017). "HEXIM1 upregulation significantly improved JQ1 efficiency in inhibiting glioma cell lines’ proliferation and cell death." (PMID 28484091, 2017). "The function of ubenimex in enhancing JQ1 treatment sensitivity of glioma cells by blocking autophagic degradation of HEXIM1 was previously studied." (PMID 29296201, 2017). "Our previous study demonstrated that ubenimex could enhance glioma's JQ1 sensitivity by blocking autophagic degradation of HEXIM1, indicating the importance of autophagy in glioma treatment." (PMID 29296201, 2017). "Our previous study has demonstrated the function of ubenimex in enhancing JQ1 treatment sensitivity of glioma cells by blocking autophagic degradation of HEXIM1; however, the detailed mechanism of autophgy regulation by ubenimex remains unclear." (PMID 29296201, 2017). "Our research confirmed that HEXIM1 is critical in regulating JQ1 sensitivity in glioma cells." (PMID 28484091, 2017).
latent infection (2 papers, 2016 to 2023). "The upregulation of transcripts of BBC3, GADD45A, MDM2, TP53I3, and downregulation of HEXIM1 during latent infection was confirmed as significant by RT-qPCR." (PMID 27898737, 2016). "The expression of several factors implicated in the inhibition of viral transcription elongation, such as PCF11 (4.3-fold), GPS2 (2.6-fold), HEXIM1 (3.7-fold), and HEXIM2 (2.7-fold), was significantly upregulated in latent infection compared to actively infected cells." (PMID 38038477, 2023).
viral infection (2 papers, 2018 to 2024). "In this way, UBE2O likely acts to potentiate transcription by ubiquitinating HEXIM1 and promoting its sequestration in the cytoplasm, a mechanism co-opted by Tat during viral infection." (PMID 29845934, 2018). "However, as a major inhibitor of P-TEFb, the connection of HEXIM1 to virus infection has been limited to HIV." (PMID 38363111, 2024). "In the absence of viral infection, RNAPII S2P (the specificity has been tested) was uniformly distributed in the nucleus regardless of whether HEXIM1 was highly expressed or knocked down." (PMID 38363111, 2024).
acute lymphoblastic leukemia (1 paper, 2021). Leukemia with an acute onset, characterized by the presence of lymphoblasts in the bone marrow and the peripheral blood. "Thus, in line with what was reported in T cell acute lymphoblastic leukemia cells exposed to JQ1 or to the BET degrader dBET6, our data indicate that HEXIM1 levels do not appear an appropriate pharmacodynamic marker for BET degraders." (PMID 36046113, 2021).